TGM2 (transglutaminase 2)
Diseases named in the same sentence as TGM2 in open-access papers (continued):
Sharing a sentence is not in itself a finding about the gene and the disease.
colorectal cancer (31 papers, 2014 to 2025). A primary or metastatic malignant neoplasm that affects the colon or rectum. "For instance, TGM2 has been linked to chemoresistance in colorectal cancer by activating the Wnt/β-catenin signaling pathway." (PMID 41469519, 2025). "Recent studies showed that upregulation of TGM2 was associated with poor prognosis in hepatocellular carcinoma, colorectal cancer, non-small cell lung cancer, or laryngeal cancer." (PMID 25247996, 2014). "Indeed, TGM2 is linked to miR-19-mediated invasion in colorectal cancer cells." (PMID 28415794, 2017). "Compared with normal cells, the expression of TGM2 in colon cancer cells is lower, and TGM2 is a potential growth suppressor of colon cancer in colorectal cancer cells." (PMID 37115802, 2023). "TGM2 regulated angiogenesis and apoptosis in colorectal cancer, which is highly expressed in VSMCs of diseases, especially in disease a." (PMID 35800890, 2022). "TGM2-siRNA knockdown attenuated colorectal cancer cell growth through the wnt3a/β-catenin/cyclin D1 pathway." (PMID 34202278, 2021). "Functioning as an upstream inhibitor to control the expression of transglutaminase-2 (TG-2), miR-19a enhances cell invasion and metastasis of colorectal cancer." (PMID 29050336, 2017). "In this work, TGM2 was reported to activate the Wnt/β-catenin signaling, which was consistent with previous studies revealing the relation of TGM2 and Wnt signaling in osteoarthritis and vascular calcification as well as other diseases such as colorectal cancer and bronchopulmonary dysplasia." (PMID 36872331, 2023). "Study in colorectal cancer showed that loss of TFAP2A delayed progression through S-phase into G2-M and decreased phosphorylation of AKT, which were mediated through regulation of TGM2." (PMID 37859819, 2023). "Moreover, downregulation of TG2 is reported to promote colorectal cancer cell invasion and miR-19-induced TGM2 depletion leads to induction of invasion and metastasis in colorectal cancer." (PMID 35261562, 2021). "Similar findings in TGM2 expression levels in primary and metastatic lesions have been described for colorectal cancer cell lines as well as for tissues from patients with colorectal cancer." (PMID 30108682, 2018). "However, the mechanism and role of TGM2 in colorectal cancer are poorly understood." (PMID 34103685, 2021). "We also performed an expression analysis of ETS1 and TGM2 with TCGA colorectal cancer datasets and verified that the expression level of ETS1 positively correlated with that of TGM2." (PMID 31570702, 2019).
type 1 diabetes (29 papers, 2008 to 2025). "Previous works have reported increased abundance of TGM2+ M2 macrophages in highly pro-inflammatory disease states, such as asthma, type 1 diabetes, sepsis, and celiac disease." (PMID 40467990, 2025).
glioblastoma (28 papers, 2012 to 2025). The most malignant astrocytic tumor (WHO grade IV). "Coincidentally, previous studies have proved that TGM2 was upregulated in Glioblastoma patients and associated with tumor progression and poor prognosis." (PMID 39457544, 2024). "TGM2 is implicated in a number of cancers, including glioblastoma, endometrial cancer, and renal clear cell carcinoma." (PMID 36765657, 2023). "Here we show that glioblastoma-associated macrophages are a major source of TGM2 in glioblastoma." (PMID 40610434, 2025). "We found that low levels of hsa-miR-17-5p expression are associated with shorter survival of glioblastoma patients in the TCGA cohort and that expression of hsa-miR-17-5p is inversely correlated with TGM2 expression in this cohort set, however, not with HOTAIRM1 expression." (PMID 34584066, 2021). "In their approach, transglutaminase 2 (TG2) was utilized as an activator, given its overexpression in glioblastoma multiforme (GBM) and its association with cancer progression." (PMID 39866911, 2025). "Thus, in addition to the epigenetic modulation of HOXA1 and the sponging hsa-miR-129-5p and hsa-miR-495-3p, sponging of hsa-miR-17-5p (and potentially other TGM2-binding miRNAs) by HOTAIRM1 may cause increased TGM2 mRNA and protein expression in glioblastoma." (PMID 34584066, 2021). "Analysis of multiple databases shows that myeloid cells are a major source of TGM2 mRNA in glioblastoma." (PMID 40610434, 2025). "As a first step to determine if TGM2 has a functional role in glioblastoma efferocytosis, the ability of TGM2-selective inhibitors to inhibit efferocytosis was tested in cell culture." (PMID 40610434, 2025). "In studies of transglutaminase 2 (TGM2), we observed that TGM2 mRNA expression in glioblastoma was primarily in a subset of tumor-infiltrating myeloid cells with hypoxia gene expression signatures." (PMID 40610434, 2025). "NC9 treatment of organoids from three different glioblastoma patients resulted in an increase in apoptotic cells, showing that TGM2 inhibition in this clinically relevant context inhibited efferocytic clearance of apoptotic cells." (PMID 40610434, 2025). "Analysis of TGM2 mRNA levels in the TCGA 2013 glioblastoma dataset (152 patients) using cBioportal showed significantly higher expression in the mesenchymal subtype." (PMID 40610434, 2025). "Overall, these data indicate that myeloid cells (particularly macrophages) are a major source of TGM2 mRNA in glioblastoma tumours." (PMID 40610434, 2025). "The data here show that efferocytosis is active in glioblastoma and can be suppressed in clinically-relevant organoid models by TGM2 inhibition." (PMID 40610434, 2025). "TGM2 mRNA expression was also present in a subset of glioblastoma cells, in agreement with previous literature, although this is lower than the expression in either endothelial cells or myeloid cells." (PMID 40610434, 2025). "Future experiments should assess TGM2 inhibitor delivery strategies in clinically relevant animal models of glioblastoma, along with efficacy experiments as a single agent and in combination with standard therapy and immune checkpoint inhibition." (PMID 40610434, 2025). "To determine if TGM2 showed similar expression patterns in human glioblastoma, we performed TGM2 immunohistochemistry on whole sections from patients." (PMID 40610434, 2025). "Specifically in glioblastoma, TGM2 has been found to be preferentially expressed in mesenchymal subtype glioblastoma and its inhibition in a subset of glioblastoma cells reduces proliferation in cell culture and in a xenograft model." (PMID 40610434, 2025). "This same pattern of high TGM2 expression in myeloid cells and endothelial cells was also observed in immunohistochemical analyses of a patient xenograft model and in human glioblastoma samples." (PMID 40610434, 2025).
glioblastoma (continued). "Analysis of xenograft and human glioblastoma samples by immunohistochemistry showed that macrophages in the vicinity of necrotic regions expressed very high levels of TGM2." (PMID 40610434, 2025). "Previous research has shown that in glioblastoma, TGM2 enhances radioresistance by promoting the fusion of autophagosomes and lysosomes through its interaction with SDC1." (PMID 39375892, 2025). "Previous studies have also identified inhibition of TGM2 as a potential target to enhance cancer cell death and chemosensitivity, e.g., in glioblastoma." (PMID 37443286, 2023). "It was also observed that lncRNA HOTAIR correlates with the expression of transglutaminase 2 (TGM2) in glioblastoma cells." (PMID 36077530, 2022). "HOTAIRM1 knock-out reduces cell viability, invasion, proliferation, and colony formation of glioblastoma cells through decreased expression of TGM2 (transglutaminase 2) and improves radiation sensitivity." (PMID 36499136, 2022). "HOTAIRM1 knock-down decreased expression of transglutaminase 2 (TGM2), a candidate protein implicated in mitochondrial function, and knock-down of TGM2 mimicked the phenotype of HOTAIRM1 down-regulation in glioblastoma cells." (PMID 34584066, 2021). "Our data shows that HOTAIRM1 promotes TGM2 expression in glioblastoma cells, which is related to miRNA-mediated mechanisms implicating hsa-miR-17-5p." (PMID 34584066, 2021). "In GBM cells, Id1 is also a potential downstream effector of protein tyrosine kinase 7(PTK7) and transglutaminase 2 (TGM2) which are highly expressed in CD44-high glioblastoma and predicts unfavorable prognosis." (PMID 32410828, 2020). "This suggests that macrophages are a major source of TGM2 mRNA in glioblastoma." (PMID 40610434, 2025). "When grown in physiologic oxygen concentrations, patient glioblastoma organoids actively engaged in efferocytosis and this could be blocked by TGM2 inhibition." (PMID 40610434, 2025). "Given the well-established immunosuppressive role for efferocytosis, blocking intratumoral efferocytosis via TGM2 inhibition may be a promising new way to sensitize glioblastoma to these immunotherapies." (PMID 40610434, 2025). "Moreover, TGM2 represents a potential therapeutic target, as TGM2 inhibition promotes cell death and chemosensitivity in in vivo models of glioblastoma." (PMID 36765657, 2023). "Moreover, our data suggest a novel role for HOTAIRM1 in regulating mitochondrial function and ROS levels in glioblastoma cells by modulating expression of TGM2, potentially by functioning as a miRNA sponge." (PMID 34584066, 2021). "The role of TGM2 in glioblastoma-associated immune cells has not been studied to date." (PMID 40610434, 2025). "Reduced TGM2 mRNA and protein levels in HOTAIRM1 stable knock-down LN-229, as well as other glioblastoma cell lines (U87MG, LN-18, and SF126) relative to control-transfected cells, were confirmed by RT-qPCR and Western blotting." (PMID 34584066, 2021).
lung carcinoma (27 papers, 2010 to 2025). "In the context of lung cancer, two cohort studies involving patients with NSCLC have identified TGM2 as a crucial biomarker associated with increased tumor invasiveness, metastatic potential, and poor prognosis." (PMID 41050683, 2025). "Collectively, investigating the functional mechanisms of TGM2 has significant clinical implications for improving lung cancer diagnosis and treatment efficacy, as well as prolonging patient survival." (PMID 41050683, 2025). "For instance, aldolase A, an interacting partner of TGM2, has been found to promote lung cancer metastasis, likely via its interaction with actin and the subsequent alteration in histone–actin interactions." (PMID 36831672, 2023). "Recently, TGM2 was found to promote migration and invasion in lung cancer cell metastasis, although the involvement was more likely the consequence of translocation rather than transamidase activity." (PMID 36831672, 2023). "S100-A8, thymidine phosphorylase, annexin A2, transglutaminase 2, and annexin A1 were lung cancer individuals’ most renowned over-expressed proteins." (PMID 36552956, 2022). "Molecularly, in lung cancer cells TGM2 appears to promote DNA damage repair upon its translocation to the nucleus and interaction with topoisomerase IIα, further highlighting that the presence of TGM2 in the nucleus is a trigger for a number of events related to cancer progression." (PMID 36831672, 2023). "TGM2 has been shown to enhance the migration and invasion of lung cancer cells." (PMID 35962453, 2022). "Interestingly, TGM2 suppression greatly reduced MMP9 expression in a lung cancer cell line suggesting that TGM2 may influence MMP9 expression also in skin." (PMID 32575800, 2020). "The HIF, TGM2, CSNK1A1, CSNK2A1, CTNNA1, NAMPT)/Visfatin, TNFRSF1A, ETS1 and SRC-1 were down-regulated and proposed as the biomarkers for lung cancer." (PMID 23122428, 2012). "Expression analysis reveals that hypoxia induced lung cancer related biomarkers, HIF and its modulating proteins (TGM2, CSNK1A1, CTNNA1, NAMPT/Visfatin, TNFRSF1A, ETS1, SRC-1, FN1, APLP2, DMBT1/SAG, AIB1 and AZIN1) are significantly down regulated." (PMID 23122428, 2012). "In gene expression profiling studies of lung cancer cell lines to study therapeutic drug sensitivity, PLAU and CDH1 have been suggested as novel biomarkers of cetuximab sensitivity, and TGM2 was suggested as a potential marker of doxorubicin sensitivity." (PMID 20142997, 2010).
dermatitis herpetiformis (21 papers, 2012 to 2025). "Patients with dermatitis herpetiformis (DH) make auto‐antibodies to transglutaminase 2 (TG2) and transglutaminase 3 (TG3)." (PMID 37424036, 2023).
Alzheimer disease (19 papers, 2012 to 2025). A progressive, neurodegenerative disease characterized by loss of function and death of nerve cells in several areas of the brain leading to loss of cognitive function such as memory and language. "Recent research suggests that transglutaminase 2 (TG2) plays a critical role in Aβ peptide aggregation in Alzheimer’s disease (AD), contributing to the neurotoxic effects associated with Aβ accumulation." (PMID 40431119, 2025). "In addition, TGM2 has also been implicated in the etiology of several neurological disorders such as Huntington's disease, Alzheimer's disease (AD), Parkinson's disease (PD) and schizophrenia." (PMID 22389694, 2012). "Overexpression of TGM2 is also observed in Huntington and Alzheimer’s diseases." (PMID 23068602, 2012). "Transglutaminase 2 (TG2) is the most studied and expressed isoform of the TG family which is important in cross-linking proteins in Alzheimer’s disease." (PMID 32717806, 2020).
Huntington disease (19 papers, 2012 to 2025). Huntington disease (HD) is a rare neurodegenerative disorder of the central nervous system characterized by unwanted choreatic movements, behavioral and psychiatric disturbances and dementia. "TGM2 has maladaptive roles in neurodegenerative diseases such as Parkinson’s disease, multiple sclerosis (MS), amyotrophic lateral sclerosis, and Huntington’s disease, and mediates the polyamination of proteins associated with neurodegenerative diseases (e.g., Tauopathies and Huntington's disease)." (PMID 33054763, 2020). "Cys‐D, a Tgm2 inhibitor, can cross the blood–brain barrier, and is commonly used in studies of brain gliomas, Huntington disease, and Parkinson disease." (PMID 39749582, 2025). "Zainelli and colleagues later revealed the direct relationship between mHtt, TGM2, and CaM in Huntington’s disease." (PMID 39769187, 2024). "TGM2 activity contributes to the severity of tissue damage in mouse models of amyotrophic lateral sclerosis, Huntington’s disease, multiple sclerosis, and stroke." (PMID 33054763, 2020). "Finally, the ablation of the Tgm2 gene or inhibition of TGM activity reduces the extent of tissue damage in stroke, MS, and Huntington’s disease." (PMID 33054763, 2020).
liver fibrosis (19 papers, 2009 to 2026). "H&E showed more porphyrin in Tgm2−/− group compared to WT group, and Masson's staining demonstrated increased liver fibrosis in Tgm2−/− mice." (PMID 38623945, 2024). "For instance, increased cross-linking mediated by transglutaminase 2 (TG2) was found in the ECM during the early inflammatory stage of liver fibrosis." (PMID 34842803, 2021). "We also provided evidence that TGM2 regulates TGF-β1 of Sj origin and IL-13 of the host and documented the important involvement of TGM2 in liver fibrosis during Sj infection in previous studies." (PMID 29321784, 2017). "We have provided evidence that TGM2 regulates the TGF-β1 of parasite origin and IL-13 of the host as well as documented the important role of TGM2 in liver fibrosis during Sj infection." (PMID 29321784, 2017). "In our previous work, we found that treating mice with CTM, a TGM2 inhibitor, decreased the levels of TGM2 and liver fibrosis in the 8-week Sj-infected mouse liver." (PMID 29321784, 2017). "Collectively, these results establish a novel positive feedback regulation in which Sj infection activated TLR4 signal pathway increases the expression of TGM2, which in turn contributes to HSCs activation through TLR4 pathway and then causes liver fibrosis." (PMID 29321784, 2017). "In previous work, we had reported that a high level of transglutaminase 2 (TGM2) is crucial for liver fibrosis post Sj infection." (PMID 29321784, 2017). "Transglutaminase 2-deficient mice injected with VEGF display a 50% reduction in angiogenesis and liver fibrosis compared to wild-type mice, indicating that transglutaminase 2 is involved in Tgf-β activation." (PMID 24484528, 2014). "Our previous work indicated that TGM2 contributes to liver fibrosis post Sj infection." (PMID 29321784, 2017). "The novel self-reinforcing molecular feedback loop between the TLR4 pathway and TGM2 may represent a potential new target in Sj infection-induced liver fibrosis and even other related liver diseases." (PMID 29321784, 2017). "Transglutaminase 2, a multifunctional enzyme, is reportedly involved in liver fibrosis." (PMID 29321784, 2017). "Furthermore, Masson's staining results demonstrated that supplementation with rhBMP7 relieved the liver fibrosis caused by the absence of Tgm2 in DDC‐induced cholestasis." (PMID 38623945, 2024). "We have shown that the positive feedback regulation between transglutaminase 2 (TGM2) and TLR4 signaling in HSCs correlated with liver fibrosis after Sj infection." (PMID 34034779, 2021). "In general, the positive feedback regulation between TGM2 and TLR4 signaling in HSCs correlated with liver fibrosis post Sj infection." (PMID 29321784, 2017). "TGM2 and TLR4 levels display a similar pattern of expression changes that correlates with the extent of liver fibrosis post Sj infection." (PMID 29321784, 2017). "This novel connection between TGM2 and TLR4 pathway activation in liver fibrosis induced by Sj infection enhances our understanding of liver diseases." (PMID 29321784, 2017). "Results showed that the level of FN was correlated with the level of TGM2, TLR4, and the extent of liver fibrosis during Sj infection." (PMID 29321784, 2017). "Thus, both TGM2 and activation of the TLR4 signal pathway correlated with the development of liver fibrosis during Sj infection." (PMID 29321784, 2017). "However, the relationship among TLR4 signaling, TGM2, and liver fibrosis in HSCs has never been reported in the literatures." (PMID 29321784, 2017). "Tgm2(−/−) mice were not used in this study to verify the results because of the inconsistent effect of CTM treatment in the early and late stages of liver fibrosis." (PMID 29321784, 2017).
neuroblastoma (18 papers, 2009 to 2025). Neuroblastoma (NB) is the most common solid, extracranial childhood tumor. "Seven of our hits (Tubb1, Tubb5, Eef1a1, Eef1g, Gapdh, Nudc, Actg1) are present in their list of 52 enriched proteins from TGM2 stimulated N2a neuroblastoma cells." (PMID 41142754, 2025). "TGM2 is localized both extracellularly and intracellularly and is also found in the nucleus in neuroblastoma cells." (PMID 36878712, 2023). "Preliminary results showed that the induction of TGM2 gene transcription and enzyme activity is essential for the differentiating effects of retinoids in neuroblastoma cells." (PMID 32085516, 2020). "Studies show that RA increases the expression of transglutaminase 2 (TG2), as seen in different cell types: neuroblastoma cells, glial cells, macrophages, rat hepatocytes, and human hepatocarcinoma cells, where it has been implicated in contributing to chemoresistance during chemotherapy." (PMID 40869421, 2025). "Retinoic acid treatment results in increased TGM2 expression in human neuroblastoma SH-SY5Y cells, and TGM2 may contribute to neuronal differentiation through the cAMP-CREB pathway." (PMID 36831225, 2023).